IL6 (interleukin 6)
Diseases named in the same sentence as IL6 in open-access papers (continued):
Sharing a sentence is not in itself a finding about the gene and the disease.
coronary artery disease (continued). "Clearly, a decrease in the proinflammatory cytokines IL-1 and IL-6 (such as in the Ac-CAD subgroup) following a diet rich in n-3 PUFA-enriched eggs may have direct implications for coronary artery disease pathogenesis and recovery from an acute incident." (PMID 34440006, 2021). "In EAT from patients with coronary heart disease (CHD), the levels of APN decreased, while the levels of IL-6, TNF-α, and Toll-like receptor 4 increased." (PMID 34456867, 2021). "After adjusting for gender, smoking, and coronary heart disease, there were significant correlations between intracranial arteriosclerosis and plasma ANP, PAI-1, TNF-α and IL-6 levels." (PMID 32548044, 2020). "Numerous reports have demonstrated a close relationship between level of hs-CRP, monocyte chemoattractant protein 1 (MCP-1), interleukin-6 (IL-6), interleukin-8 (IL-8), and tumor necrosis factor (TNF)-α with pathogenesis of coronary heart disease." (PMID 32178701, 2020). "In the diabetic animals, we observed increased TNF-α and IL-6 levels, and these alterations were improved with TMZ administration, which is coherent with a previous study in patients with stable coronary artery disease." (PMID 33680027, 2020). "Given that CVD is a major cause of mortality in T2DM, CRP has been proven to be a better predictor for coronary heart disease than other inflammatory markers, such as tumor necrosis factor alpha (TNF-α) and IL-6." (PMID 31208420, 2019). "Serum CP-IgA, hs-CRP and IL-6 levels increased with the severity of the coronary artery disease (P < 0.05), and the serum hs-CRP and IL-6 levels of patients with perioperative cardiovascular events were higher (P < 0.05)." (PMID 31088358, 2019). "In that study, they showed that IL-1, IL-6, IL-6sR, and TNF-alpha expression was greater in epicardial adipose tissue than that in subcutaneous adipose tissue among patients with coronary artery disease." (PMID 30862094, 2019). "Inflammatory biomarkers (IL-6 and TNF) were shown to decrease in patients with coronary heart disease." (PMID 31316451, 2019). "In patients with coronary artery disease, compared with SOC, POC triggered more increments of IL-6 that is an indicator of inflammation." (PMID 31248029, 2019). "In this study, we detected the serum MIAT concentration in 102 patients with coronary heart disease and 89 healthy subjects by QRT-PCR and detected the concentrations of IL-6 and TNF-α in peripheral blood by ELISA." (PMID 31143478, 2019). "In case of suffering from coronary artery disease (CAD), the epicardial adipose tissue displayed significantly higher levels of chemokine (MCP-1) and several inflammatory cytokines (IL-1β, IL-6, IL-6sR, and TNF-α), comparing to subcutaneous adipose tissue." (PMID 28757877, 2017). "Both IL-6 and CRP are widely used markers for systemic inflammation and predictors of coronary heart disease." (PMID 24229441, 2013). "Specifically, patient age, gender, ischemic vs. non-ischemic heart disease, LVEF, IL-6 and TNF-α serum levels and the need for mechanical circulatory support were tested as continuous or categorical variables, respectively." (PMID 24074138, 2013). "High circulating interleukin-6 concentration is associated with increased risk of coronary heart disease in observational studies and preliminary evidence suggests a variant in the gene for its receptor (IL6R) might be associated with reduced risk of coronary heart disease." (PMID 22421340, 2012). "We sought to evaluate the relationship between proinflammatory cytokine levels (TNF-alpha, IL-6) and tissue Doppler derived indices of LVDD in patients with stable coronary artery disease." (PMID 19909503, 2009). "Third, whereas IL-6 levels have been associated with adverse myocardial remodeling following MI, firm data on the effect of IL-6 inhibition on post-MI remodeling in patients with coronary artery disease are lacking." (PMID 41543641, 2026).
coronary artery disease (continued). "In a 12-week study, non-obese men and post-menopausal women with coronary heart disease were provided with 30 g/day of flaxseed: the intervention group showed lower IL-6 and TNF-α levels than the control group." (PMID 40944222, 2025). "Indeed, EAT samples from patients with coronary artery disease (CAD) undergoing coronary artery bypass grafting have exhibited higher interleukin 1Bꞵ and 6 (IL‐1ꞵ, IL‐6), and tumor necrosis factor‐alpha (TNF‐α) compared with subcutaneous fat depots." (PMID 39943721, 2025). "Pentraxin 3 (PTX3) emerges as a promising future biomarker for detecting vascular inflammation in coronary artery disease (CAD), offering greater specificity than hsCRP or IL-6 by localizing primarily to atherosclerotic lesions rather than reflecting systemic inflammation." (PMID 41511355, 2025). "A Mendelian randomized analysis showed that the anti-inflammatory effect of statins on coronary heart disease does not involve the IL-6 signaling pathway." (PMID 39596487, 2024). "Recently, IL-36 has aroused great interest because of its dysregulation in inflammatory diseases, in fact the serum levels of IL-36 were found to be significantly higher with coronary artery disease, correlated with TNF-α, IL-6 and IL-32 levels and coronary artery stenosis." (PMID 38961336, 2024). "Since inflammation is thought to play a significant role in the etiology of coronary artery disease, the levels of inflammatory biomarkers, such as IL-6, CD40,c-reactive protein (CRP), complement, and myeloperoxidase (MPO), can be used to gauge the severity and prognosis of coronary artery disease." (PMID 38084332, 2023). "For instance, inflammatory cytokines IL-6 and TNF-α could be the main targets of miR-296a, and their expression was abnormal in peripheral blood mononuclear cell of patients with coronary artery disease." (PMID 37507655, 2023). "We found that patients who failed CPAP were older, had higher baseline IL-6, D-dimer, CURB-65, and blood urea, as well as worse oxygenation parameters and higher respiratory rate, and were more likely to be affected by ischemic heart disease, COPD, and chronic kidney failure." (PMID 36498759, 2022). "While a relation exists between white blood cell counts and the incidence of coronary heart disease in epidemiologic studies, elevated peripheral white blood cell and monocyte counts, hs-CRP, interleukin-6, and adhesion molecules have been demonstrated in CAS patients." (PMID 35096275, 2022). "So far, there are no studies analyzing the role of interleukin 6, consequently inflammation, in the diagnosis and prognosis of patients with ischemic heart disease through microvascular involvement, and even less so in female patients." (PMID 34683106, 2021). "Autophagy is an essential component of RIPC-induced cardioprotection that may upregulate autophagy through an IL-6/JAK-STAT-dependent mechanism, thus identifying a potentially new therapeutic option for the treatment of ischemic heart disease." (PMID 32121587, 2020). "With the aggravation of the severity of the coronary artery disease, the serum CP-IgA, hs-CRP and IL-6 levels gradually increased in patients with CHD, all were significantly higher, when compared to those in the control group, and the differences were statistically significant (P = 0.000)." (PMID 31088358, 2019). "Importantly, a recent study reported lower expression of miR-10a and simultaneous higher expression of IL-6 and TNF-α in peripheral blood mononuclear cells (PBMCs) of patients with coronary artery disease (CAD) compared to control subjects." (PMID 30013975, 2018). "There is also evidence that IL-6 and TNF-α could act as mediators in the incidence of depressive symptoms in patients with some other diseases, such as coronary artery disease or multiple sclerosis." (PMID 27918465, 2016).
coronary artery disease (continued). "In patients with coronary artery disease (CAD), adiponectin mRNA expression was markedly decreased in EAT, whereas multiple pro-inflammatory adipocytokines mRNA expression, including chemerin, IL-1β, IL-6 and TNF-α, were significantly increased." (PMID 27352781, 2016). "Therefore, the persistent cellular infiltration of the adventitia of aneurysms was associated with an increased M-CSF and PPARγ expression, while the aorta of patients with coronary artery disease showed higher level of chemokine CCL2 and cytokine IL-6." (PMID 26539497, 2015). "High levels of IL-6 and CRP predicted incident coronary heart disease." (PMID 25722960, 2015). "Also in patients with coronary artery disease and chronic kidney disease, SDMA and IL-6 levels were correlated." (PMID 23158556, 2012). "Concentrations of C-reactive protein (CRP), serum amyloid A, and interleukin-6 were increased in patients with coronary heart disease but failed to correlate with acuteness of coronary disease." (PMID 19662190, 2007). "Previous research reported that the expression of hsa-miR-320a was related to an increase in inflammatory cytokines such as IL-6, MCP-1, or TNF-α, and may inhibit human-derived endothelium cell proliferation and induce apoptosis that may promote atherogenesis in coronary artery disease." (PMID 37298699, 2023). "In patients with coronary artery disease, the local expression of chemokine (monocyte chemotactic protein 1 (MCP1)) and inflammatory cytokines (IL-1β, IL-6, and TNF-α) was observed with significant changes in MCP1, IL-1β, IL-6, TNF-α mRNA, and protein in the epicardial adipose stores." (PMID 36768479, 2023). "In this study we determined IL-6 and IL-1Ra changes after prognostic treadmill test (as a stressor maneuver) to compare the levels of selected plasma cytokine levels between opium-addicted and non-opium addicted male patients with coronary artery disease." (PMID 23028694, 2012). "Further, in T2D hypertensive patients with coronary artery disease, 12 months of receiving GE containing Resv (8 mg) did not alter the blood pressure, glucose, or inflammatory markers except for a significant decline in alkaline phosphatase and Interleukin-6 (IL-6)." (PMID 27294953, 2016). "Importantly, the serum level of IL-6 and TLR4 endogenous ligand HMGB1 was significantly higher in patients with coronary artery diseases (CAD) than in healthy subjects." (PMID 27563891, 2016). "In our study, IL-6 levels do not correlate with CAD progression, and it seems IL-6 has minimal or no direct pro-inflammatory or anti-inflammatory effects in specific contexts within coronary artery disease." (PMID 39330316, 2024). "Factors predicting reduced responses included older age, Child-Turcotte-Pugh B/C, and elevated IL-6 in cirrhosis; non-mRNA vaccine in AILD; and coronary artery disease, use of mycophenolate and dysregulated B-call activating factor, and lymphotoxin-α levels in LT." (PMID 37870985, 2023).
heart failure (472 papers, 2009 to 2026). Inability of the heart to pump blood at an adequate rate to meet tissue metabolic requirements. "IL-6, on the other hand, is a major contributor to chronic inflammation and is linked to the progression of heart failure by promoting hypertrophy and interstitial fibrosis." (PMID 40427493, 2025). "Early landmark European data demonstrated that circulating interleukin-6 (IL-6) is a robust, independent predictor of all-cause mortality and heart failure hospitalization across the spectrum of ejection fraction." (PMID 41375916, 2025). "Impaired NK cell cytolytic function was associated with baseline IL-6 levels in PBMCs of heart failure patients." (PMID 40360833, 2025). "Pro-inflammatory cytokines including tumor necrosis factor-α (TNF-α), interleukin-1 (IL-1), and interleukin-6 (IL-6) exhibit close associations with the pathogenesis of heart failure." (PMID 41526164, 2025). "Heart failure is associated with the induction of pro-inflammatory cytokines, of which IL-6 and TNF-α are commonly used inflammatory factors." (PMID 40951892, 2025). "Some biomarkers, such as CRP, IL-6, and IL-1β, related to aging or diseases, such as heart failure and cancer, are associated with MCI." (PMID 40281902, 2025). "Chronic inflammation, a hallmark of both frailty and heart failure, is characterized by elevated levels of proinflammatory cytokines such as interleukin-6 and C-reactive protein, which contribute to muscle wasting and functional decline." (PMID 40149736, 2025). "Specifically, the inflammatory markers hs-CRP, IL-1β, and IL-6 were significantly positively correlated, suggesting that these markers jointly participate in the inflammatory response associated with heart failure." (PMID 41333015, 2025). "Among emerging biomarkers, interleukin-6 (IL-6 pg/mL), a master regulator of inflammation, has consistently been associated with left ventricular hypertrophy, progression of heart failure, and increased mortality." (PMID 41450363, 2025). "For example, IL-1 blockade has been shown to reduce the risk of heart failure in patients with MI,14,15 and a large clinical trial of IL-6 inhibition in patients with MI is ongoing (NCT06118281)." (PMID 41134248, 2025). "The cardiosplenic axis has an important causal role in heart failure in numerous animal studies, and its activation would be mediated precisely by IL-6 upon solicitation of mononuclear cells." (PMID 38397422, 2024). "Higher IL-6 levels were associated with reduced systolic function in apparently healthy individuals, which perhaps served as a predictive marker for heart failure." (PMID 38256155, 2024). "Compared to Th1 cells, a greater number of Th17 cells co-secrete TNF-α and IL-6, which are associated with heart failure." (PMID 37175422, 2023). "Myocarditis and DCM can be characterized by elevated Th17 pathogenesis and release of the associated cytokines TGF-β1, IL-6, IL-23, and granulocyte-macrophage colony-stimulating factor (GM-CSF), which are correlated with heart failure." (PMID 37175422, 2023). "DNMT3A mutated monocytes from patients with heart failure have been shown to express higher mRNA levels of IL-1β, IL-6 and IL-8, macrophage inflammatory chemokines CCL3 and CCL4 and the inflammasome NLRP3." (PMID 36835370, 2023). "IL-6 is an independent predictor of all-cause mortality, cardiovascular death, and subsequent heart failure hospitalization in patients recently hospitalized with decompensated HFpEF." (PMID 36896709, 2023). "In patients recently hospitalized with heart failure with preserved ejection fraction, IL-6 is an independent predictor of all-cause mortality, cardiovascular death, and sHFH after adjustment for risk factors including BNP." (PMID 36896709, 2023). "Patients with higher circulating concentrations of IL-6 were at an increased risk of all-cause death, cardiovascular death, and subsequent heart failure hospitalization." (PMID 36896709, 2023).
heart failure (continued). "The severity of CAD,coronary events, mortality, and the onset of heart failure have all been associated to IL-6 levels." (PMID 38250529, 2023). "The increase in IL6 level indicates the risk of heart failure with preserved ejection fraction (HFpEF) over time." (PMID 36832048, 2023). "Increased levels of interleukin-1 (IL-1) and interleukin-6 (IL-6) have been linked to detrimental cardiac remodeling and unfavorable outcomes in individuals with heart failure." (PMID 37664375, 2023). "Elevated blood interleukin-6 concentrations have also been associated with increased heart failure–related mortality." (PMID 37445494, 2023). "Th17 cells and their associated cytokines (i.e., IL-17A, IL-6, IL-23) were found to directly correlate with heart failure in a study of patients with clinically suspected myocarditis/acute DCM." (PMID 36937911, 2023). "High plasma levels of Stromal Cell-Derived Factor 1 (SDF-1), IL-1β and IL-6 were associated to cardiac inflammation, heart failure and cardiovascular mortality." (PMID 36158826, 2022). "TNF-α and IL-6 are implicated in the pathophysiology of heart failure and of pulmonary hypertension." (PMID 35307783, 2022). "Ischaemic heart disease, especially acute coronary syndrome (ACS) and heart failure, are significantly associated with IL-6 and have been implicated as a diagnostic marker by some authors." (PMID 36013520, 2022). "More importantly, ‘inflammaging’ has been suggested as a major risk factor for the development of heart failure in geriatric patients following hip fracture and has been mostly linked to elevated systemic levels of IL-6 and TNF." (PMID 36131923, 2022). "Meanwhile, numerous studies have demonstrated that elevated IL-6 level was associated with cardiac events, including incidence of heart failure, unstable angina, acute kidney injury, and functional status outcomes for patients after cardiac surgery." (PMID 36263090, 2022). "Interleukin-6 (IL-6) is an important player in chronic inflammation associated with heart failure and tumor-induced cachexia." (PMID 35967380, 2022). "Circulating levels of cytokines: IL-1β, TNFα, IL-10, IL6, IL-8 and IL-12 were determined and investigated regarding their association with hemodynamic parameters, clinical signs of heart failure and outcome." (PMID 36014020, 2022). "IL-6 is a pro-inflammatory cytokine implicated in the pathogenesis of hypertrophy and heart failure." (PMID 32857156, 2021). "The importance of inflammation was also demonstrated by the close association between IL-6 and LV function suggesting a role in adverse LV remodelling and potential development of heart failure." (PMID 34933964, 2021). "Over the median follow-up of 3.7 years, those with hsCRP or IL-6 levels in the highest tertile at baseline were at a two-fold increased risk of heart failure hospitalisation compared to those in the lowest tertile." (PMID 34199975, 2021). "The levels of inflammatory factors IL-6 and IL-1β are positively associated with heart failure severity." (PMID 34658880, 2021). "Several pro-inflammatory cytokines, including tumor necrosis factor-alpha (TNF-alpha), interferon-gamma, interleukin-1-beta, interleukin-6, interleukin-17, and interleukin-18 have been implicated in the pathogenesis of heart failure." (PMID 33391898, 2021). "Recent research has shown elevated levels of IL-6 in 56% of patients with heart failure and an association with poorer clinical outcome in this setting." (PMID 33122738, 2020). "For example, a high level of circulating IL-6 is a strong predictor of clinical outcomes associated with advanced LV dysfunction, which causes heart failure in myocarditis, cardiomyopathy, or allograft rejection." (PMID 32392882, 2020). "Heart failure development is associated with an elevated expression of multiple pro-inflammatory cytokines, and both IL-6 and TNFα are associated with left ventricular remodeling and myocyte hypertrophy." (PMID 32271823, 2020).